TLR4 (toll like receptor 4)
Diseases named in the same sentence as TLR4 in open-access papers (continued):
Sharing a sentence is not in itself a finding about the gene and the disease.
coronary artery disease (continued). "Importantly, the serum level of IL-6 and TLR4 endogenous ligand HMGB1 was significantly higher in patients with coronary artery diseases (CAD) than in healthy subjects." (PMID 27563891, 2016). "Given the role of inflammatory activation by TLR4 in atherogenesis, our finding of LBP in human coronary artery plaques in vivo, and plaque-derived systemic release of LBP are novel findings that justify further consideration of LBP as a pathogenic factor in coronary artery disease." (PMID 28642677, 2017). "In EAT from patients with coronary heart disease (CHD), the levels of APN decreased, while the levels of IL-6, TNF-α, and Toll-like receptor 4 increased." (PMID 34456867, 2021). "The toll-like receptor 4 (TLR4)-myeloid differentiation factor 88 (MyD88)-dependent signaling pathway plays a role in the initiation and progression of coronary artery disease (CAD)." (PMID 26959040, 2016). "A recent study of patients with coronary artery disease (CAD) receiving ARB, ACEI, and statins for 12 months provided evidence of Toll-like receptor 4 (TLR-4) regulated microRNAs." (PMID 26064773, 2015). "With respect to the underlying signaling, while TLR4-MyD88 signaling is involved in HMGB1 binding to platelets for impairing myocardial repair and in trauma, the importance of RAGE and not TLR4 has been reported in coronary artery disease and in NET." (PMID 32731558, 2020). "Toll-like receptor 4 (TLR4) expression is increased in activated monocytes, which play a critical role in the pathogenesis of coronary artery disease (CAD)." (PMID 30857550, 2019). "Toll-like receptor 4 (TLR4) is known to be involved in innate immunity and inflammatory responses that play important roles in the pathogenesis of coronary artery disease (CAD)." (PMID 27652106, 2016). "Analysis of our qPCR data showed no statistical difference in platelet TLR4 and TLR 9 mRNA expression in patients with ACS when compared patients with coronary artery disease excluded by angiography." (PMID 31644579, 2019). "It should be noted that monocyte TLR4, but not TLR2, is upregulated in ischemic heart disease patients with ‘reduced EF’." (PMID 26030867, 2015).
Autoimmunity (55 papers, 2008 to 2026). The occurrence of an immune reaction against the organism's own cells or tissues. "The protein encoded by this TIRAP gene, is related to the TLR4 signaling pathway and plays an important role not only in innate immunity but also in autoimmunity." (PMID 38028622, 2023). "It is possible that METH causes similar TLR4 signaling defects in B cells, skewing the production of inflammatory mediators resulting in faulty Ab production and significant tissue damage via autoimmunity, massive and sustained immune cell infiltration, or flawed responses to microbial infection." (PMID 34109323, 2021). "Furthermore a missense polymorphism in the TLR4 gene has been associated with a number of autoimmune conditions, including Crohn diseases, making TLR4 a viable candidate gene for investigation." (PMID 26830904, 2016). "However, there is emerging evidence that excessive TLR4 activation may be pathogenic in human diseases affecting the central nervous system, cardiovascular, respiratory and metabolic systems, thereby promoting inflammation and autoimmunity." (PMID 41869302, 2026). "NF-κB, a signaling intermediate located distally in both BCR and TLR4 pathways, has been demonstrated to be hyperactive in other models of autoimmunity." (PMID 40985892, 2025). "Toll like receptor 4 (TLR4), a pathogen-associated molecular pattern (PAMP) receptor, is known to exert inflammation in various cases of microbial infection, cancer and autoimmune disorders." (PMID 37153546, 2023). "S100A8 is an mRNA targeted by ENSRNOT00000078133, a major leukocyte protein secreted by activated leukocytes, and binds to Toll-like receptor 4 to promote inflammation and autoimmunity." (PMID 36434596, 2022). "Expression of tlr on mouse FDCs has been shown by immunohistochemistry (tlr4) and functionally in a tlr7 knock-out mouse model of autoimmunity." (PMID 34424268, 2021). "TBK1-mediated production of type I IFN can also be triggered by the stimulation of Toll-like receptor 4 (TLR4) with bacterial lipopolysaccharide (LPS) in murine models of autoimmunity." (PMID 33916318, 2021). "TLR4 is expressed on melanocytes and believed to react to endogenous heat-shock proteins and initiate autoimmunity by stimulating dendritic cells (DCs) to present melanocyte-specific antigens to T cells in lymphoid tissues." (PMID 34468896, 2021). "Currently, several lines of evidence showed that TLR4 relates to the pathophysiology of various diseases as well as autoimmunity." (PMID 30877182, 2019). "The alarmin S100A8/A9 expressed by granulocytes and monocytes is released by activated phagocytes and as an endogenous TLR4 agonist promote inflammation during infection, autoimmunity, and cancer." (PMID 30105034, 2018). "It is reported that MRP8 also acts as an endogenous activator of TLR4 and promotes inflammatory processes in infection and autoimmunity by amplifying TNF-α release in response to LPS." (PMID 29902248, 2018). "In C57BL6lpr/lpr mice, a model of spontaneous autoimmunity, TLR2 or TLR4 deficiency limits the expansion of the marginal zone B cell compartment and attenuates the levels of antinuclear-antibodies and rheumatoid factors." (PMID 29650017, 2018). "Obviously, the immunostimulatory functions of TLR4 can trigger the initiation of autoimmunity in permissive genetic constellations even when aberrant TLR-4/IL-1 signaling is restricted only to dendritic cells." (PMID 29650017, 2018). "Mesangial cells isolated from NZB/W mice with spontaneous autoimmunity express significantly higher levels of TLR4 and produce significantly more pro-inflammatory chemokines under baseline and LPS-stimulated conditions." (PMID 29650017, 2018). "There is also an evidence have been reported that the mutant R243L increased activation of CAPN5 catalytic core domain to stimulate TLR4 autoimmunity inflammation in CAPN5R243L transgenic mice retina." (PMID 29245980, 2017).
Autoimmunity (continued). "Regulatory T-cells (Tregs) express TLRs which are activated by endotoxin and TLR4 hyper function in vivo potentiates Treg function to curtail TLR4-dependent autoimmunity." (PMID 24465843, 2014). "For example, their interaction with TLR4 increased the systemic autoimmunity and promoted the endotoxin-induced lethality." (PMID 23637971, 2013). "We have demonstrated that these proteins act as endogenous activators of TLR4 and promote inflammatory processes in infections and autoimmunity." (PMID 22489132, 2012). "We have recently demonstrated, that S100A8/A9 complexes are endogenous activators of TLR4 and via this signaling pathway they promote inflammatory processes in infections and autoimmunity." (PMID 22489132, 2012). "By maturing WT or IL-12 deficient BMDCs with Poly I∶C or LPS and pulsing mature DCs with GP peptides, the impact of TLR3 or TLR4 stimuli on the requirement for IL-12 in breaking tolerance and inducing autoimmunity can be evaluated." (PMID 21931625, 2011). "NEC-mediated dysregulated genomic pathways are associated with innate immune responses, e.g., cytotoxicity, inflammation, NK-mediated immunity, and autoimmunity, and are consistent with the involvement of eNAMPT/TLR4 signaling-influenced genes in NEC pathobiology." (PMID 38790933, 2024). "The top CFA11 SNP was located within a lncRNA gene adjacent to TLR4. lncRNAs may be involved in autoimmunity through the regulation of neighboring genes." (PMID 33243158, 2020). "Indeed, in contrast to TLR4, the dysregulation of TLR9 signaling has been associated with autoimmunity, even though its precise role is still a subject of debate." (PMID 30900780, 2019). "Furthermore, exposing anti-ds DNA transgenic mice to TLR4 agonistic LPS aggravates systemic autoimmunity and LN." (PMID 29650017, 2018). "Also, autoantibody levels of anti-dsDNA and anti-RNP were both decreased indicating the requirement of TLR4 for the full-blown autoimmunity." (PMID 29650017, 2018). "Moreover, we also saw increased levels of IL1alpha which is downstream of TLR4 signaling, as a downstream mechanism of autoimmunity pro-inflammation." (PMID 29245980, 2017). "The present finding of intact sBGN in SF, together with the recognition of sBGN as an endogenous damage-associated molecular pattern-type ligand for TLR2/TLR4 and for P2X7/4, provides a third mechanism of relevance for autoinflammation, co-stimulation and autoimmunity." (PMID 26703441, 2015). "Also data in mice indicate that TLR4 plays a key role in mediating autoimmunity, proinflammatory cytokine production, and other immune activation." (PMID 26613049, 2015). "Previous studies have indicated that TLR-mediated activation of T cells can directly promote the development of autoimmunity and TLR-4-stimulation can activate the antigen presenting cells sufficiently to deliver the signals required to drive the pathogenic function of the T cell." (PMID 26236564, 2015). "We have established a murine model to examine whether TLR3 or TLR4 mediated DC maturation has an impact on the cytokines required to break tolerance and induce T-cell-mediated autoimmunity." (PMID 21931625, 2011). "Therefore, because TLR2 cannot recognize bacterial HSP60, perhaps the abnormal recognition of HSP60 by TLR4 is the beginning of normal autoimmunity in NTG." (PMID 20057905, 2009). "Besides autoimmunity, it remains unknown whether the increased TLR4 expression accounts for the LPS-sensitizing controls of infection." (PMID 37138358, 2023). "However, there are few studies on B cell TLR4 signaling in autoimmunity." (PMID 37872565, 2023). "Thus, long-term repeated stimulation of bacterial products may induce breakdown of B cell tolerance as shown in previous studies that altered BCR and microbial TLR signals (e.g., TLR4 and MyD88) may promote the breakdown of autoimmunity." (PMID 37027536, 2023).
Autoimmunity (continued). "TLR4 can also signal through TRIF to activate IRF3 and type I interferons, which, though antiviral, can become dysregulated in aging and autoimmunity." (PMID 41373468, 2025). "Toll-like receptor 4 (TLR4) and its co-receptor CD14 play a crucial role in autoimmunity by recognizing endogenous ligands, mainly autoantigens." (PMID 37176151, 2023). "AIM-100, an inhibitor of ACK1, can significantly inhibit TLR4/TLR7/TLR9-induced activation of macrophages and DCs and alleviates the TLRs-mediated inflammation and autoimmunity." (PMID 35669783, 2022). "Pharmaceutical inhibition of PKM2 by PKM2-IN can inhibit TLR4/TLR7/TLR9-induced activations of macrophages, DCs and B cells, and alleviate the pathogenesis of TLRs-mediated inflammation and autoimmunity." (PMID 34025679, 2021). "In this review, we have discussed up‐to‐date knowledge of the regulation of the pathways elicited by TLR4 and TLR9 and their roles in host defense and autoimmunity." (PMID 30900780, 2019). "We demonstrated that the transfer of TLR3 or TLR4 matured DCs presenting self-antigens promotes CD8 T cell mediated autoimmune responses and overt organ specific autoimmunity in vivo." (PMID 21931625, 2011). "Taken together, these results confirmed our hypothesis that ACK1 promotes TLR4/TLR7/TLR9-induced activation of macrophages and DCs, therefore contributes to the pathogenesis of TLR-mediated inflammation and autoimmunity." (PMID 35669783, 2022). "Toll-like receptors (TLRs) play critical roles in the activation of innate immunity and we have previously shown that antibody triggering of TLR4 and TLR5 may contribute to autoimmunity." (PMID 25514237, 2014). "These are TLR4 and RAGE receptors, known to play a role in infection, autoimmunity, and cancer." (PMID 25371673, 2014). "Two pattern recognition receptors, Toll-Like receptor 4 (TLR4) and receptor for advanced glycation end products (RAGE), have shown to be involved in S100A8/A9-mediated pathologic effects such as infection, autoimmunity and cancer." (PMID 23637971, 2013). "Interestingly, the role of toll like receptor 4 (TLR4) has been critically investigated for mediating inflammatory responses in various cases of microbial infections, immune regulation in cancer and autoimmunity." (PMID 37153546, 2023). "TLR2 and TLR4 silencing in CD14++ monocytes of these patients prevents Treg differentiation to Th1-like Tregs and thus IFN-γ secretion by Tregs of these patients, suggesting that autoimmunity is promoted by CD14++ monocytes predominantly through activation of inflammatory signaling pathways." (PMID 30072988, 2018). "TLR2 and TLR4 bind to components of gram positive and gram negative bacteria which could be a pathognomonic factor in autoimmunity." (PMID 26339139, 2015). "Interestingly, Toll-like receptor 4 (TLR4) is the cognate receptor for LPS and its activation can induces up-regulation of other TLRs, such as TLR7 (the receptor for TMEV) and 9, known to be involved in autoimmunity." (PMID 19094215, 2008). "Considering that dysfunction or dysregulation of TLRs, especially TLR4, TLR7, and TLR9, leads to a series of pathological conditions, we investigated whether ACK1 regulates the activation of the TLR signaling pathway and participates in the pathogenesis of inflammation and autoimmunity." (PMID 35669783, 2022).
myocarditis (55 papers, 2007 to 2025). Myocarditis is a condition that is characterized by inflammation of the heart muscle (myocardium). "In viral myocarditis caused by Coxsackievirus B3, TLR4-deficient mice show reduced inflammation and myocarditis due to decreased viral replication." (PMID 38790263, 2024). "By binding TLR4, SARS-CoV-2 triggers rampant inflammation and ALI, and as it enters the blood circulation, it infects the heart via ACE2 and/or TLR4 (causing myocarditis), as well other organs such as the skin, kidneys, and GI tract where TLR4 is expressed." (PMID 33505220, 2021). "Mice deficient in TLR4 or TLR9 show attenuated myocarditis phenotypes accompanied by reduced production of inflammatory cytokines." (PMID 34504807, 2021). "TLR4-deficient mice had significantly reduced myocarditis severity, viral replication, and IL-1β/IL-18 after infection with enteroviruses such as CVB3." (PMID 30046376, 2018). "In silico structure modeling predicted a potential interaction between the concave leucine-rich surface of OGN and the extracellular LRR domain of TLR4 that has been implicated in CVB3-myocarditis disease severity." (PMID 27878326, 2017). "Mice were additionally treated with PAM3CSK4 (TLR2 agonist) or ultrapure LPS (TLR4 agonist) on the same day as CVB3 infection or 3 days post infection to confirm their role in myocarditis susceptibility." (PMID 23241283, 2012). "While previous reports demonstrated a pathogenic role for TLR4 this is the first report that TLR2 is preferentially up-regulated in CVB3 infected female mice or that signaling through this TLR directly causes myocarditis resistance." (PMID 23241283, 2012). "The increase in myocardial TLR4 mRNA expression was associated with enteroviral replication and cardiac dysfunction in human myocarditis." (PMID 21977329, 2011). "TLR4 deficient mice infected with CVB3 develop significantly reduced acute myocarditis that correlates with reduced interleukin (IL)-1β and IL-18 levels in the heart, indicating that TLR4 signaling increases inflammation in the heart." (PMID 23675015, 2007). "Furthermore, TLR4-deficient mice had significantly less myocarditis and more resistance to CVB3 infection with less viral replication than wild-type mice." (PMID 33505220, 2021). "TLR4 signaling was also associated with increased proinflammatory cytokines (IL-1β and IL-18) expression in the infected hearts, suggesting these two cytokines play an important role in the pathogenesis of CV-induced myocarditis." (PMID 21977329, 2011). "However, direct inhibition of TLR4 may not be a promising therapeutic avenue to improve the prognosis of myocardial inflammation to some extent, since TLR4 inhibition may lead to a functional loss of the innate immune mechanism." (PMID 27228349, 2016). "Most cardiac inflammatory cells during acute myocarditis at day 10 pi are CD11b+ (macrophages and mast cells) that express TLR4 and release IL-1β." (PMID 39696682, 2024). "Both PEV and pmPEV contained miRs that inhibited key pathways of the pathogenesis of myocarditis like the TLR4/inflammasome pathway." (PMID 39835120, 2024). "Studies in mouse models demonstrate that TLR4-deficient mice exhibit increased resistance to CVB3 infection, showing decreased inflammatory responses, viral replication, and myocarditis compared to wild-type mice." (PMID 38790263, 2024). "Fairweather’s model showed that the dominant innate (first minutes and hours) and adaptive (during acute myocarditis at day 10 after infection) immune response in males is characterized by upregulation of complement and TLR4 on macrophages and mast cells." (PMID 36937911, 2023). "A role of TLR4 in SARS-CoV-2-induced myocarditis has been proposed since it binds with high affinity to the SARS-CoV-2 spike protein." (PMID 36982447, 2023).